TGFA (transforming growth factor alpha)
Description:
TGF alpha is a mitogenic polypeptide that is able to bind to the EGF receptor/EGFR and to act synergistically with TGF beta to promote anchorage-independent cell proliferation in soft agar.
Synonyms: TFGA
Tractability: Antibody: a drug acting on it is in phase 2 or 3 trials; its Gene Ontology location is reachable by antibodies, with high confidence; UniProt places it where antibodies can reach, with medium confidence; UniProt predicts a signal peptide or a membrane-spanning region.
Gene: Protein-coding gene on chromosome 2 (70,447,284 to 70,554,193, reverse strand). Ensembl gene ENSG00000163235.
Subcellular location: Secreted, extracellular space (Transforming growth factor alpha); Cell membrane (Protransforming growth factor alpha)
Subcellular location (Human Protein Atlas): Vesicles; Predicted to be secreted
Pathways (Reactome):
Signal Transduction: EGFR downregulation; EGFR interacts with phospholipase C-gamma; Estrogen-dependent gene expression; Estrogen-dependent nuclear events downstream of ESR-membrane signaling; Extra-nuclear estrogen signaling; GAB1 signalosome; GRB2 events in EGFR signaling; PI5P, PP2A and IER3 Regulate PI3K/AKT Signaling; PIP3 activates AKT signaling; RAF/MAP kinase cascade; SHC1 events in EGFR signaling; Signaling by EGFR
Vesicle-mediated transport: COPII-mediated vesicle transport; Cargo concentration in the ER; Cargo recognition for clathrin-mediated endocytosis; Clathrin-mediated endocytosis
Developmental Biology: Developmental Lineage of Mammary Gland Luminal Epithelial Cells; Developmental Lineage of Mammary Gland Myoepithelial Cells
Disease: Constitutive Signaling by Aberrant PI3K in Cancer; Inhibition of Signaling by Overexpressed EGFR
Gene expression (Transcription): TFAP2 (AP-2) family regulates transcription of growth factors and their receptors
Gene Ontology:
Molecular function: epidermal growth factor receptor binding; growth factor activity; protein binding; receptor ligand activity
Biological process: cell surface receptor signaling pathway; epidermal growth factor receptor signaling pathway; ERBB2-EGFR signaling pathway; positive regulation of epithelial cell proliferation; positive regulation of MAPK cascade; intracellular signal transduction; positive regulation of cell population proliferation; positive regulation of mitotic nuclear division; hepatocyte proliferation
Cellular component: basolateral plasma membrane; cell surface; cytoplasmic vesicle; extracellular region; perinuclear region of cytoplasm; clathrin-coated endocytic vesicle membrane; endoplasmic reticulum membrane; endoplasmic reticulum-Golgi intermediate compartment membrane; ER to Golgi transport vesicle membrane; plasma membrane
Genetic constraint (gnomAD): Loss-of-function variants: 12 observed, 19.52 expected, observed/expected ratio (o/e) 0.61, 90% interval 0.39 to 1. The upper end of that interval is the gene's LOEUF score, 1, which puts it in group 4 of 6, group 1 being the genes least tolerant of losing a copy. Missense variants: 178 observed, 199.83 expected, observed/expected ratio (o/e) 0.89, 90% interval 0.79 to 1.01. Synonymous variants: 79 observed, 84.51 expected, observed/expected ratio (o/e) 0.93, 90% interval 0.78 to 1.13.
Homologues: Orthologues: pig TGFA (96% identical), rabbit TGFA (95% identical), guinea pig TGFA (94% identical), macaque TGFA (93% identical), chimpanzee TGFA (92% identical), mouse Tgfa (92% identical), dog TGFA (80% identical), tropical clawed frog tgfa (72% identical), rat Tgfa (63% identical), zebrafish tgfa (44% identical). Paralogues in human: BTC (26% identical), EPGN (19% identical), EREG (19% identical), HBEGF (19% identical), AREG (16% identical).
Diseases named in the same sentence as TGFA in open-access papers:
TGFA is named in the same sentence as 303 diseases in open-access papers, as found by Europe PMC text mining. Sharing a sentence is not in itself a finding about the gene and the disease. The quoted sentences say what the papers report.
breast cancer (91 papers, 1990 to 2026). A primary or metastatic malignant neoplasm involving the breast. "TGFA encodes a growth factor that is a member of the epidermal growth factor family, regulating autocrine in breast cancer cells." (PMID 39513664, 2024). "In TGFα-driven breast cancer incidence, reduced serum Ahsg contributed to a delay in breast cancer progression in FGFR4-deficient mice by altering metabolic pathways such as adipogenesis." (PMID 39684629, 2024). "TGFA was also linked to estrogen-receptor-expressing breast cancer, and its role in breast cancer progression was proposed." (PMID 37511575, 2023). "TGFα-EGFR signaling was found to be significantly affected in all examined breast cancer cell lines in response to estrogen and strongly associated with the level of WWOX expression, especially in ER-positive MCF7 cells." (PMID 35290621, 2022). "As shown, all examined breast cancer cell lines show differential expression genes of TGFα-EGFR signaling which is associated with WWOX protein level." (PMID 35290621, 2022). "There was previously reported that TGFα elevated expression together with ADAM17 expression in breast cancer is associated with lymph node metastasis and worse survival prognosis." (PMID 35290621, 2022). "Elevated levels of TGFα in the serum of breast cancer patients were associated with a poor response to lapatinib/capecitabine." (PMID 27933395, 2017). "qRT-PCR was performed to assess expression levels of EREG, AREG, EGF, HB-EGF and TGFα, all of which have been implicated in breast cancer." (PMID 26215578, 2015). "Among the cytokines and chemokines, we found that TGFα significantly modulated LIF that has been demonstrated to be associated to breast cancer transformation and progression." (PMID 25344915, 2014). "Additionally, TGFA overexpression has been linked to malignancies such as breast cancer and multiple myeloma." (PMID 40152768, 2025). "This was determined in a study earlier investigating the role of the naturally occurring mutation Asp351Tyr in ER-negative MDA-MB-231 breast cancer cell line stably transfected with DNA constructs for expression of either wild-type ER or the Asp351Tyr mutant ER and the endogenous TGFα reporter gene." (PMID 35360069, 2022). "TGFA has been described as a factor that is produced by tumor cells and is circumstantially implicated in the regulation of the autocrine growth of breast cancer cells; TGFA overexpression may occur during malignant progression." (PMID 30916164, 2019). "Of these, HBEGF is abundantly expressed in human adipose tissue, TGFα has been implicated in the development of obesity-related postmenopausal breast cancer using rodent models, and EGF has received much attention as a therapeutic target in anticancer therapies." (PMID 27525640, 2017). "Another protein ERα-regulated protein from TGFα-EGFR is PLCB1 which was recently identified as a metastatic breast cancer driver gene." (PMID 35290621, 2022). "Based on the observation that the levels of expression of miR-23c and miR-379-3p were reduced in conditioned media from TGFα-stimulated MSCs, we investigated the effects of the downregulation of these miRNAs in breast cancer cells." (PMID 35406622, 2022). "Our findings showed that such TGFα-EGFR carcinogenic action can be enhanced in breast cancer with low expression of WWOX tumor suppressor gene which is supposed to be a very common event in this tumor." (PMID 35290621, 2022). "In the breast cancer xenograft model, reduction of MMP-1 expression significantly inhibited breast cancer growth, brain metastasis, and lung metastasis through reducing TGFa release and phosphor-EGFR expression." (PMID 35037689, 2022). "To summarize, TGFα-EGFR is regulated in breast cancer mostly by estradiol through ERα regulation of TGFα expression." (PMID 35290621, 2022). "ADAM17 promotes progression of breast cancer by regulating levels of TGFα, which plays a pivotal role in this pathological process." (PMID 33579029, 2021).
breast cancer (continued). "In a recent histological analysis of patients with breast cancer bone metastases, tissue surrounding the tumors exhibited increased macrophage coverage as well as increased TGFα expression compared to the tumor tissue." (PMID 33069212, 2020). "While the immunomodulatory role of TGFα has not been previously investigated in ovarian cancer, increased TGFα expression has been correlated with increased levels of macrophages in breast cancer." (PMID 33069212, 2020). "It is known that T3 plays a role in the development and progression of breast cancer, by inducing the expression of progesterone receptors and increasing the mRNA levels of proto-oncogenes, such as the transforming growth factor α (TGFA)." (PMID 30916164, 2019). "Several EGF ligands have been implicated in breast cancer, including EGF, epiregulin (EREG), amphiregulin (AREG), heparin-bound EGF (HB-EGF) and transforming growth factor alpha (TGFα)." (PMID 26215578, 2015). "It is noteworthy that δ-tocols were found to stimulate TGFα expression in vitro in human breast cancer cells." (PMID 26779438, 2015). "MSCs express functional epidermal growth factor receptor (EGFR) and breast cancer cells secrete EGFR-ligands including transforming growth factor-α (TGFα)." (PMID 25344915, 2014). "High levels of expression of TGFα have been reported in several tumor types, including breast cancer." (PMID 25344915, 2014). "We have demonstrated that tamoxifen inhibits transforming growth factor alpha (TGFα) gene expression in human breast carcinoma samples treated in vitro with T3." (PMID 24587767, 2014). "The network analysis indicated alterations in a number of cancer related pathways, including p38 MAPK, PI3K/AKT, ERK/MAPK and NF-κB signaling pathways, and a potential role of TGFA, ErbB2, and IL-1/IL-1R in young women with breast cancer." (PMID 23704896, 2013). "Specifically in the context of breast cancer, resveratrol inhibits TGFα resulting in the elevated expression of TGFβ2." (PMID 23840623, 2013). "Thus the mechanisms underlying the delay of TGFα-driven breast cancer development by the FGFR4 deficit may be related to metabolic activities of FGF21/19 that cause systemic metabolic programming that in turn impacts local metabolic, and therefore, cellular effects such as the decrease in mitoses." (PMID 24279986, 2013). "We investigated mechanisms by which the FGFR4 deficit led to the delay in breast cancer progression driven by the overexpression of TGFα." (PMID 24279986, 2013). "The addition of an MMP-1 inhibitor in further experiments confirmed that MMP-1 activity can modulate levels of TGFα in culture supernatants of the breast cancer cell lines." (PMID 23217186, 2012). "Certain growth factors augment oncogenic c-Myc expression in human breast cancer, including TGFα and IGF-I." (PMID 22226054, 2012). "EGFR and its ligand, transforming growth factor-alpha (TGF-alpha) play an important role in several human cancers, through the autocrine growth-regulation system in breast cancer, EGFR has been reported to be associated with a poor clinical outcome." (PMID 17092354, 2006). "Oestrogens and antioestrogens modulate the synthesis of transforming growth factor alpha (TGF-alpha) in breast cancer cells." (PMID 9667651, 1998). "However, the inhibitor of carboxypeptidase from potatoes was also reported to exert cytotoxic activity by acting as an epidermal growth factor (EGF)/ transforming growth factor alpha (EGF/TGF-alpha) antagonist in the MDA-MB-453 breast cancer cell line." (PMID 38769554, 2024). "A number of the early mammary cancer studies were performed with the mouse mammary tumor virus (MMTV)-transforming growth factor-alpha (TGF-α) transgenic mouse model - a cancer model in which TGF-α overexpression is under the control of the MMTV promoter." (PMID 33987528, 2021). "In addition, TGFA has been illustrated to be positively related to several cancers, such as prostate cancer, colon cancer, and breast cancer." (PMID 33661995, 2021).
breast cancer (continued). "EGFR antibody or specific kinase inhibitors can block the TGF-α/EGFR signaling pathway and prevent breast cancer growth induced by TGFA overexpression, suggesting that this pathway may play an important role in cancer treatment." (PMID 32020849, 2021). "In vitro, knocking down TGFA did not reduce breast cancer cell production of MCSF, but did reduce the expression of CCL2, leading the authors to conclude that breast cancer cell-derived TGFα induced autocrine EGFR signaling, leading to increased CCL2 and macrophage recruitment." (PMID 33069212, 2020). "Additionally, knockdown of TGFA in a human breast cancer cell line used in a mouse model of breast cancer decreased the total number of macrophages present in the tumors as well as tumor growth." (PMID 33069212, 2020). "We have shown that on exposure to physiological T3 concentrations, there was an increase in the TGFA expression in a breast cancer cell line after 4 h, which suggests that further studies should be done to determine the effects of transcription blocking drugs on breast adenocarcinoma cell lines." (PMID 30916164, 2019). "Furthermore, TGFα expression was found to be induced by trastuzumab application in breast cancer patients." (PMID 27933395, 2017). "Furthermore, co-treatment of BT-474 breast carcinoma cells with TGFα and trastuzumab neutralized the inhibition of the cell growth by trastuzumab." (PMID 27933395, 2017). "Indeed, ErbB2 amplification is a hallmark of human breast cancer, and a number of ErbB ligands are highly expressed in breast tumors, including the EGFR ligand TGFα and the ErbB3/ErbB4 ligand HRG." (PMID 27351228, 2016). "Because several studies demonstrated that MSCs express a functional EGFR, we hypothesized that TGFα might be involved in the cross-talk between MSCs and breast cancer cells within the tumor microenvironment." (PMID 25344915, 2014). "Indeed, by combining TGFα overexpression in breast epithelial cells and the FGFR4 deficiency outside the breast, we found that ablation of FGFR4 reduced TGFα-driven breast cancer incidence, delayed breast cancer progression and improved host survival." (PMID 24279986, 2013). "Moreover, we performed immunohistochemical staining in breast cancer patient samples using antibodies directed against TGFA, IL1RN and PI3K." (PMID 23704896, 2013). "Our previous classification of SERMs in these two cell lines was based on one single marker of E2-responsiveness in these breast cancer cells: E2 and 4OHT produced oestrogenic effects on the activation of TGFα mRNA in cell expressing wtERα whereas Ral and ICI were anti-oestrogens." (PMID 12177783, 2002). "Moreover, TGFA facilitates breast cancer metastasis to the bones." (PMID 37511575, 2023). "MMP-1 has been proposed as a biomarker for breast cancer; understanding its role in activation of the TGFα/EGFR signal pathway may lead to the use or development of additional targeted agents to suppress this axis, and result in improved treatments for metastatic breast cancer." (PMID 23217186, 2012). "Meanwhile, TGFα-induced EGFR activation has been reported to promote tumor progression in cervical cancer, ovarian cancer, and breast cancer." (PMID 39885395, 2025). "TGFA also promotes cell proliferation and epithelial-mesenchymal transition (EMT) in prostate, liver, and breast cancers." (PMID 35686121, 2022). "In addition, as MDA-MB-468 and MDA-MB-231 cells express EGF-related ligands, we can hypothesize that breast cancer cells, through the secretion of TGFα, educate MSCs to promote breast cancer progression by repressing miRNAs that act as tumor suppressors, such as miR-23c." (PMID 35406622, 2022). "The present study aimed to analyze the differential expression of genes related to growth factors such as FGF2, FGFBP1, TGFA, TGFBR3, and IGF1R in a radiation- and estrogen-induced experimental breast cancer model." (PMID 36430763, 2022).
breast cancer (continued). "For example, TGFA can regulate the transformation of mammary epithelial cells, and TGF-α and epidermal growth factor receptor (EGFR) are overexpressed in human breast cancer tissues and various breast cancer cell lines." (PMID 32020849, 2021). "For example, overexpression of Transforming growth factor-alpha (TGF-α), one of the main ligands of the EGFR, has been observed in various of malignant tumors such as kidney cancer, pancreatic cancer, colon cancer and breast cancer." (PMID 26503469, 2015). "In breast cancer cells Rac1 is a downstream effector of ErbB receptors and mediates migratory responses by ErbB1/EGFR ligands such as EGF or TGFα and ErbB3 ligands such as heregulins." (PMID 23533813, 2013). "The results demonstrated that active MMP-1 proteolysed latent TGFα to generate active TGFα, leading to an activated EGFR signal pathway, thus linking MMP-1 and the EGFR signaling pathway in metastatic breast cancer cells." (PMID 23217186, 2012). "The TGFA levels were shown to be higher in breast cancer patients when compared with non-cancerous individuals, which indicates the role of TGFA in breast cancer carcinogenesis." (PMID 37511575, 2023). "In addition, increased TGFα and VEGF were seen in MDA-MB-231 breast cancer cells and thus influenced cell proliferation, invasion and angiogenesis." (PMID 34182543, 2021). "In cell culture, breast cancer cells with secondary resistance to trastuzumab displayed an up-regulation of mRNA expression for EGF, TGFα, HB-EGF and heregulin, while the expression of AREG mRNA was downregulated and the expression of epiregulin and betacellulin mRNA was unchanged." (PMID 27933395, 2017). "The same dataset was also used previously to demonstrate the impact of abnormal expression of TACE, TGFA, and AREG, which were shown to play important roles in the HMT3522 series of the breast cancer cells grown in the 3D culture, on the survival of the same cohort of the breast cancer patients." (PMID 25057922, 2014). "Therefore, we sought to compare the effects of two other EGFR ligands relevant to mammary gland development and breast cancer, AREG and TGFα, on K5+K19- hMEC cell differentiation." (PMID 24124521, 2013). "We quantitated the surface target density of Ep-CAM and HER-2 on nine breast cancer cell lines, which were of different tumour source and differed with respect to the status of oestrogen receptor expression, HER-2 amplification and expression of FGF and TGFα." (PMID 15655555, 2005). "Furthermore, the results suggest that all these markers should be used in the earlier stages of the disease, since an analysis of BRCA patients indicated that the FGF2, FGFBP1, TGFA, TGFBR3, and IGF1R gene expression levels were present in late stages 3 and 4 of breast cancer." (PMID 36430763, 2022). "In a breast cancer mouse model, mucin 1 (MUC1 for human and Muc1 for nonhuman species) facilitated TGFα-induced EGFR activation and breast cancer development." (PMID 22457794, 2012). "Furthermore, FGF10, but not TGFα, required FGFR activation to induce EGFR_T693 phosphorylation and ERK activation in breast cancer cells expressing endogenous FGFR2b." (PMID 34086370, 2021).